ATAD2B (ATPase family AAA domain containing 2B)
Synonyms: KIAA1240
Tractability: Small molecule: a structure with a bound ligand is known; a high-quality ligand is known. PROTAC: ubiquitination databases record sites on it; its protein half-life has been measured; a small molecule that binds it is known.
Target class: Epigenetic regulator; Bromodomain; Reader
Chemical probes: BAY-850 (high quality), GSK8814 (high quality)
Gene: Protein-coding gene on chromosome 2 (23,748,664 to 23,927,164, reverse strand). Ensembl gene ENSG00000119778.
Subcellular location: Nucleus
Subcellular location (Human Protein Atlas): Nucleoplasm
Gene Ontology:
Molecular function: histone reader activity; ATP hydrolysis activity; chromatin binding; ATP binding
Biological process: nucleosome assembly; nucleosome disassembly; transcription initiation-coupled chromatin remodeling
Cellular component: nucleoplasm; nucleus
Genetic constraint (gnomAD): Loss-of-function variants: 25 observed, 92.79 expected, observed/expected ratio (o/e) 0.27, 90% interval 0.19 to 0.38. The upper end of that interval is the gene's LOEUF score, 0.38, which puts it in group 1 of 6, group 1 being the genes least tolerant of losing a copy. Missense variants: 864 observed, 1,177.7 expected, observed/expected ratio (o/e) 0.73, 90% interval 0.69 to 0.78. Synonymous variants: 417 observed, 415.32 expected, observed/expected ratio (o/e) 1, 90% interval 0.93 to 1.09.
Homologues: Orthologues: chimpanzee ATAD2B (99% identical), macaque ATAD2B (98% identical), dog ATAD2B (97% identical), pig ATAD2B (95% identical), rabbit ATAD2B (94% identical), rat Atad2b (93% identical), mouse Atad2b (92% identical), guinea pig ATAD2B (89% identical), tropical clawed frog atad2b (71% identical), zebrafish atad2b (59% identical), Caenorhabditis elegans lex-1 (29% identical). Paralogues in human: ATAD2 (48% identical).
Diseases named in the same sentence as ATAD2B in open-access papers:
ATAD2B is named in the same sentence as 6 diseases in open-access papers, as found by Europe PMC text mining. Sharing a sentence is not in itself a finding about the gene and the disease. The quoted sentences say what the papers report.
breast carcinoma (1 paper, 2022). "Oncomine and immunohistochemistry showed a high expression of ATAD2B in glioblastoma and oligodendroglioma; ATAD2B immunostaining was also increased in human breast cancer." (PMID 36008934, 2022).
cancer (3 papers, 2021 to 2026). A tumor composed of atypical neoplastic, often pleomorphic cells that invade other tissues. "In humans, ATAD2B is dysregulated in several disease states including cancer and respiratory disorders, yet despite its promise as a therapeutic target, little is known about its molecular function." (PMID 41959150, 2026). "HDAC3, HDAC10, HDAC2, HDAC7, ATAD2B were significantly upregulated in 9, 14, 13, 9, and 10 cancer types, respectively, whereas KAT2B was downregulated in 16 cancer types." (PMID 37553641, 2023). "The development of novel inhibitors selectively targeting the ATAD2 and ATAD2B bromodomains has been essential in identifying new functions for these proteins, and their contributions to cancer development." (PMID 34298819, 2021). "Much less is known about the paralogous ATAD2B gene, but it has also been reported to be more highly expressed in several other cancers including brain and breast cancer tumors." (PMID 34298819, 2021).
ATAD2B also shares sentences with these, for which no sentence is quoted: glioblastoma (1 paper); oligodendroglioma (1); respiratory disorders (1); virus infection (1).